IL1B (interleukin 1 beta)
Diseases named in the same sentence as IL1B in open-access papers (continued):
Sharing a sentence is not in itself a finding about the gene and the disease.
ovarian carcinoma (continued). "A statistically significant higher concentration of IL-1β in the serum of patients with stage G3 ovarian cancer was demonstrated compared to the reference group (p<0.01), patients with stage G1 and G2 ovarian cancer (both p<0.05)." (PMID 41561739, 2025). "We first analyzed the IL-1β protein level in an ovarian cancer TMA, ZL-OVA961, from Super Biotek Company." (PMID 40244135, 2025). "The IL-1β protein level was greater in ovarian cancer tissues, including high-grade serous carcinoma and internal carcinoma." (PMID 40244135, 2025). "Recombinant IL-1β protein and the overexpression of IL-1β decreased the proliferation and metastasis of ovarian cancer cells." (PMID 40244135, 2025). "It was shown that tumor-derived IL-1β influences β1-integrin expression, enabling the adhesion of disseminated ovarian cancer cells to mesothelium and their subsequent implantation." (PMID 39201656, 2024). "Although there was no change in M1 marker expression in both THP1 and PBMCs, there was an increase in the production of CCL20 and IL1β that subsequently enhanced ovarian cancer cell migration." (PMID 39287565, 2024). "The contribution of IL-1β to disease progression is well established in several cancers, such as skin, breast, and ovarian cancer, while its implication in other types is less understood, with some studies producing contradictory results." (PMID 39201656, 2024). "This suggests that ovarian cancer has a direct effect on the kidney’s function, as the tumor led to increase in expression levels of IL-1β, TNFα, IL6, and GDF-15." (PMID 39394174, 2024). "The expression of COX-2 in ovarian cancer cells is regulated by various cytokines, such as EGF, vitamin D, IL-1β, which can stimulate the proliferation, migration, and angiogenesis of ovarian cancer cells." (PMID 38764576, 2024). "DLX4 induces CD44 by stimulating IL-1β-mediated NF-κB activity, thereby promoting ovarian cancer metastasis." (PMID 38317839, 2024). "NLRP3 is involved in ovarian cancer chemoresistance with downregulation increasing drug sensitivity in gemcitabine‐resistant cell lines and overexpression inducing IL‐1β, EMT, and Wnt/β‐catenin signaling." (PMID 37752941, 2023). "Consistent with this, IHC staining with anti‐IL‐1β and anti‐PD‐L1 in 41 surgically resected human ovarian cancer samples demonstrated that IL‐1β was abundant in tumor tissues and positively correlated with the level of PD‐L1." (PMID 37009412, 2023). "Higher levels of IL‐1β were correlated with poorer prognosis in patients with ovarian cancer after 5 years of follow‐up." (PMID 37009412, 2023). "The results showed a positive correlation between PD‐L1 expression and IL‐1β secretion in mouse ovarian cancer ID8 tumor tissues and mouse lewis l LLC tumor tissues." (PMID 37009412, 2023). "Currently, our group found that both CCL2 and IL-1β promote the proliferation and metastasis of epithelial ovarian cancer cells." (PMID 36403055, 2022). "Further studies have shown that cytokines such as IL-1β and IL-23 are an important mediator of Th17 induction by TAMs in patients with ovarian cancer." (PMID 32148497, 2020). "Urinary and serum levels of IL-1β tend to be more elevated in patients with epithelial ovarian cancer than in healthy women." (PMID 32635472, 2020). "CD83 highly-associated genes, such as ITGAM, IL1B, CYBB, PIK3R5, BTK, and OSM, ectopically express in ovarian cancer cells or tissues, involving in ovarian cancer progression, hypoxia networks, and the development of chemoresistance." (PMID 32823589, 2020). "IL-1β produced by ovarian cancer cells induces β1 expression on mesothelial cells facilitating adhesion." (PMID 32780245, 2020).
ovarian carcinoma (continued). "Release of multiple inflammatory cytokines into the plasma, including IFNγ, IL-1β, IL-6, IL-8, IL-10, TNFα, PlGF, and HSP90B1, is frequently associated with epithelial ovarian cancers (EOC)." (PMID 26858849, 2015). "Constitutive production of IL-1β by human ovarian carcinoma cell lines enhances their invasion capacities by increasing expression of matrix metalloproteinase-1 and stimulating production of proangiogenic factors." (PMID 26357657, 2015). "In vitro, minocycline was found to significantly suppress both constitutive and IL-1β or 4-hydroxyestradiol (4-OH-E2)-stimulated IL-6 expression in human ovarian cancer cells; OVCAR-3, SKOV-3 and CAOV-3." (PMID 23593315, 2013). "Here we have shown that minocycline transiently blocks activation of ERK1/2 in IL-1β-stimulated ovarian cancer cells which rapidly is compensated due to the known rapid turnover of p-ERK1/2." (PMID 23593315, 2013). "A previous study showed that IL-1β, IL-6 and TGF-β were involved in differentiation and expansion of the Th17 cells in ovarian cancers; IL-1β and IL-6 promoted, whereas TGF-β inhibited, Th17 cell expansion." (PMID 22994684, 2012). "We investigated the expression of IL-1β in archival tissues obtained from 96 early-stage ovarian cancer cases." (PMID 22296757, 2012). "In order to link the model findings to events in human disease, we investigated the expression of IL-1β in archival tumor tissues obtained from a cohort of 96 early-stage ovarian cancer cases." (PMID 22296757, 2012). "Constitutive production of IL-1β by ovarian carcinoma cells enhances their invasion capacities by increasing expression of MMP-1 and stimulating production of proangiogenic factors such as vascular endothelial growth factor (VEGF)." (PMID 21765834, 2011). "The levels of IL-1β in the supernatant of all ovarian cancer cell lines studied were significantly higher than endometrial cells (P < 0.05)." (PMID 20181040, 2010). "Consistent with our data, TRAIL induced apoptosis is inhibited by IL8 in ovarian cancer cells, by IL-1β in keratinocytes, and by IL6 in multiple myeloma cells." (PMID 20661477, 2010). "The effect of intraperitoneal (i.p.)injection of recombinant human interleukin-1 beta (rhIL-1 beta) was studied in three i.p. nude mouse xenograft models of human ovarian cancer (HU, OS, and LA)." (PMID 1586593, 1992). "In addition, analysis revealed a positive correlation between SAA1 and IL1B expression in ovarian cancer tissues." (PMID 41029721, 2025). "The results revealed that IL-1β was overexpressed in ovarian cancer cells." (PMID 40244135, 2025). "Assessing IL-1β levels in the peritoneal fluid of women also showed, similar to IL-1α, statistically significant higher levels of IL-1β in the peritoneal fluid of women with ovarian cancer stage G3 vs. G1 (p<0.001) and G3 vs. G2." (PMID 41561739, 2025). "The level of IL-1β increased significantly in the ovarian cancer TMA, which suggested that IL-1β may play a key role in ovarian cancer." (PMID 40244135, 2025). "In addition, our results allow us to conclude that higher levels of IL-1β are found in patients with G3 stage of histological differentiation, suggesting a potential pro-tumor function of IL-1β in ovarian cancer." (PMID 41561739, 2025). "However, the role of IL-1β in the function of ovarian cancer cells is unclear and needs to be determined." (PMID 40244135, 2025). "To summarize, these results indicated the significant upregulation of IL-1β in ovarian cancer." (PMID 40244135, 2025). "Although CCL2/MCP-1 induces recruitment of monocytes, which may support CSCs in currently unidentified ways, IL1β is a known inducer of stemness in other cancers and may also be important in ovarian cancer." (PMID 39287565, 2024). "Our data illustrated that IL‐1β released from Mφ facilitated the PD‐L1 expression, which might uncover a critical mechanism in the elevation of PD‐L1 in “cold” tumors such as ovarian cancer." (PMID 37009412, 2023).
ovarian carcinoma (continued). "There is a correlation between CCL2 and IL-1β in the progression of ovarian cancer." (PMID 36403055, 2022). "AGPAT1, B2M, BASP2, IER3, and IL1B are the salivary mRNAbiomarkers for ovarian cancer detection." (PMID 37693919, 2022). "Finally, IL-1β-induced β1-integrin expression is responsible for ovarian tumor cell adhesion to mesothelia, a crucial step in ovarian cancer dissemination." (PMID 32635472, 2020). "Moreover, cancer cells and APCs from human ovarian cancer samples produce IL-1β, which favors the differentiation and expansion of Th17 cells." (PMID 32635472, 2020). "Ovarian cancers are known to induce expression of TNFα and IL-1β." (PMID 31767036, 2019). "Since L1CAM was also reported to induce IL1β in ovarian cancer, L1CAM-induced resistance in this cancer may be regulated through a similar mechanism." (PMID 31455004, 2019). "The observed cytokine reaction could explain the increase in mMDSC, since IL-6 is a known inducer of mMDSC expansion in humans and IL-1b correlates with mMDSC in blood of ovarian cancer patients." (PMID 31214202, 2019). "Nonetheless, urinary IL-1β levels tended to be highest in patients with benign ovarian disease and a (first degree) family history of breast and/or ovarian cancer compared to patients with benign ovarian disease, but without a family history of breast and/or ovarian cancer." (PMID 25403235, 2014). "To simulate what happens in ovarian tumors, we used IL-1β (10 ng/ml) to induce IL-6 expression in ovarian cancer cells and then examined whether minocycline can block the surge in IL-6 expression." (PMID 23593315, 2013). "Moreover, constitutive production of IL-1β by ovarian carcinoma cells stimulates production of cytokines such as IL-6." (PMID 23593315, 2013). "It is likely that IL-1B plays multiple roles in progression and/or metastasis in ovarian cancer." (PMID 22296757, 2012). "Immunohistochemical analysis of a cohort of 96 ovarian cancer cases showed that negative IL-1β expression was significantly associated with an improved overall survival rate." (PMID 22296757, 2012). "We have measured levels of IL-1α, IL-1β and IL-1RA in endometrial and ovarian cancer cells." (PMID 20181040, 2010). "Next, we determined whether IL-1β overexpression affects the function of ovarian cancer cells." (PMID 40244135, 2025). "Moreover, the level of expression of IL-1β in ovarian cancer cells was determined." (PMID 40244135, 2025). "Co-culture experiments further demonstrated that ovarian cancer cells recruit and activate MDSCs via SAA1 secretion, which engages TLR2/4 on MDSCs and induces IL-1β production." (PMID 41029721, 2025). "Our study reveals that SAA1 regulates IL-1β secretion by MDSCs through TLR2/4, while the secreted IL-1β in turn stimulates SAA1 production in ovarian cancer cells, thereby establishing a positive feedback loop between these components." (PMID 41029721, 2025). "In turn, IL-1β acts on ovarian cancer cells to enhance SAA1 expression and release via the IL-1β/IL-1R/NF-κB signaling pathway." (PMID 41029721, 2025). "The results confirmed that IL-1β significantly upregulated both the expression and secretion of SAA1 in ovarian cancer cells." (PMID 41029721, 2025). "IL-1β, in turn, upregulates SAA1 expression in ovarian cancer cells, establishing a positive feedback loop that promotes the formation of a tumor-promoting immunosuppressive microenvironment and drives ovarian cancer progression." (PMID 41029721, 2025). "NOB, a polymethoxyflavonoid, stimulates traditional autophagy, ROS production, and a decline in MMP, all of which contribute to initiating GSDMD/GSDME‐mediated pyroptosis and upregulating the expression of IL‐1β and ASC in ovarian cancer." (PMID 37752941, 2023). "We will then evaluate and determine the mechanisms involved in ovarian cancer tumor growth by measuring levels of anandamide and 2-arachidonoyl glycerol as well as protein levels of CB1, CB2, ERα, ERβ, GPER, TNFα, IL-1β and IL-6 in ovarian and tumor tissues." (PMID 35242036, 2022).
ovarian carcinoma (continued). "We observed the association of SUCNR1 expression with interleukins, including IL1B (cor = 0.473, p = 2.86e-18), IL7 (cor = 0.39, p = 1.78e-12), IL16 (cor = 0.508, p = 2.66e-21), and IL18 (cor = 0.348, p = 4.67e-10), in ovarian cancer." (PMID 33062639, 2020). "The top distinctive genes for the proliferation metaprofile include, besides previously used markers, numerous genes related to malignancy and ovarian cancer progression, in particular cytokines and their receptors: CXCL1, IL1A, CXCL8, IL1B, IL1R1, and IL1R2." (PMID 29362714, 2017). "The inflammatory cytokines IL-1β and TGF-β are reported to induce FAP expression in the highly metastatic ovarian cancer cell line HO-8910PM." (PMID 24551161, 2014). "Taken together, our research suggests that ovarian cancer cells secrete SAA1, which interacts with TLR2/4 on the surface of MDSCs, not only promoting MDSCs recruitment and GMP differentiation into MDSCs but also enhancing IL-1β secretion by MDSCs." (PMID 41029721, 2025). "We first analyzed IL-1β expression in an ovarian cancer TMA consisting of eight normal ovarian tissue samples, 47 high-grade serous carcinoma samples, and 14 internal carcinoma samples." (PMID 40244135, 2025). "Considering that IL-1β is also a potent inducer of SAA1 release, we further investigated whether IL-1β secreted by MDSCs could, in turn, stimulate SAA1 production in ovarian cancer cells." (PMID 41029721, 2025). "In ovarian cancer models, co-treatment with BMX-001 and PTX significantly reduced the cell viability of CAOV2 cells compared to PTX alone and downregulated the expression of BCL2, NF-κB, and IL-1β." (PMID 40872550, 2025). "The CX3CR1_macro subpopulation may play a role in promoting tumor progression in ovarian cancer with high expression of BAG3, IL1B, and VEGFA." (PMID 35935940, 2022). "For the following genes, we found no significant changes in expression in fibroblasts after treatment with exosomes from ovarian cancer cells: HTATIP2 (HIV-1 Tat interactive protein 2, 30 kDa), IL1B, TGFB1 and TNFSF10 (TRAIL, Tumor necrosis factor (ligand) superfamily, member 10)." (PMID 36012171, 2022). "Silencing PS1 significantly decreased the expression of IL-1β, suggesting that blocking PS1 might reverse the immunosuppression in ovarian cancer." (PMID 32587587, 2020). "Both IL-1β and TNF has been shown to regulate ovarian cancer in nude mouse xenograft models." (PMID 22296757, 2012). "As an upregulated lncRNA in ovarian cancer tissues and cell lines, HOTTIP silencing leads to NLRP1 inflammasome-mediated pyroptosis, decreases cell viability, increases the expression of pro-pyroptosis factors, like IL-18, IL-1β, and NLRP1, and activates caspase-1 in ovarian cancer cells." (PMID 39967908, 2025). "In this study, we showed that EVs from ovarian cancer cells upregulated genes related to the inflammatory response, including immune cell–attracting cytokines (CCL2, CCL3/L1, CCL15, CCL18, and CCL20), interleukins (IL1B and IL32), and cell–cell adhesion transcripts (VCAM1 and ICAM1)." (PMID 40689422, 2025). "Consequently, we will determine the mechanisms of action involved in ovarian cancer tumor growth, we will measure levels of anandamide and 2-arachidonoyl glycerol as well as protein levels of CB1, CB2, ERα, ERβ, GPER, TNFα, IL-1β and IL-6 in ovarian and tumor tissues." (PMID 35242036, 2022). "Moreover, we further performed a cytokine array analysis, and HM‐macrophages coculture caused a significant increase in many inflammatory cytokines (G‐CSF, GM‐CSF, sICAM1, IL‐α, IL‐1β, IL‐1RA, IL‐6, CCL3, and TNFα), which are known to be abundantly present in ovarian cancer ascites." (PMID 35403834, 2022). "With regards to the M1 markers, our data suggest a slight upregulation of IL-1β, IL-6, and TLR-2 expression in the presence of MSCs and reparixin, despite the fact that gene expression profiles reveal usually an M1/M2 mixed-polarization phenotype in ovarian cancer." (PMID 31504643, 2020).
ovarian carcinoma (continued). "Likewise, elevated levels of urinary IL-1β were found among OC patients with a family history of breast and/or ovarian cancer compared to OC patients from families without a family history of disease." (PMID 25403235, 2014). "Three ovarian cancer cell lines SKOV3, OVCAR8, and A2780 were administrated with or without IL‐1β, and we found that IL‐1β increased the phosphorylation of P65 (NF‐κB activation) and ERK, beginning at 30 min after treatment, compared to non‐treatment groups." (PMID 37009412, 2023). "Surprisingly, we found that IL-1β did not activate the phosphorylation of JNK in HMC3 cells when compared with TOV21G, a human ovarian cancer cell line (used as a control for JNK phosphorylation), induced by 10% fetal bovine serum (FBS) for 30 min." (PMID 32842681, 2020). "However, the relationship between IL-1β, JNK, and MMP12 in ovarian cancer has not been reported." (PMID 40244135, 2025).